REN (renin)
Diseases named in the same sentence as REN in open-access papers (continued):
Sharing a sentence is not in itself a finding about the gene and the disease.
Hypertension (continued). "Hypertension is mainly based on activation of the renin-angiotensin aldosterone system (RAAS) by renin overproduction, in WT caused by local kidney ischemia due to vascular compression by large tumors, as well as directly by the blastemal component of the WT." (PMID 35205701, 2022). "Gender-specific associations were demonstrated between hypertension and genetic polymorphisms, including components of the renin-angiotensin system, NO synthase, and aldosterone synthase." (PMID 35872884, 2022). "We investigated how IH causes hypertension and report that IH up-regulates renin mRNA in juxtaglomerular cells via the down-regulation of microRNA (miR)-203." (PMID 35682548, 2022). "In summary, we revealed an association between rs12336898 in SPTAN1 and hypertension in the low-renin group." (PMID 35448080, 2022). "Although a number of different factors have been implicated, it is generally accepted that the chronic activation of the renin–angiotensin–aldosterone system (RAAS) due to Ang II stimulation is the most important cause of hypertension in DM-2." (PMID 36140406, 2022). "Psoriatic patients also have increased renin-angiotensin system activity, vascular damage, and oxidative stress linked to psoriasis and hypertension." (PMID 34996506, 2022). "The renin‐angiotensin system (RAS) contributes to vascular disease with multiple cardiovascular risk factors including hypertension." (PMID 35681278, 2022). "Meanwhile, renal ischemia caused by hypertension activates the renin-angiotensin-aldosterone system, leading to constriction of the inlet and outlet arteries and a further increase in glomerular pressure, which aggravates renal ischemia." (PMID 35966858, 2022). "The role of miRNAs in hypertension was underlined by several studies and experimental results, especially by interfering with the renin-angiotensin-aldosterone system." (PMID 35369298, 2022). "The basic treatment for IgA nephropathy consists of removing risk factors, in particular hypertension, with blockade of the renin-angiotensin-aldosterone system." (PMID 36281086, 2022). "We found CpGs previously associated with hypertension and kidney function to be associated with concentrations of renin and aldosterone, and we found one DMP annotated to the NR3C2 gene of the RAAS system to be associated with ARR." (PMID 36457109, 2022). "It is thought that TWIST1 upregulates C3 to induce the EMT phenomenon that activates the intrarenal renin-angiotensin system and is associated the pathogenesis of hypertension." (PMID 36018840, 2022). "Additional causes of hypertension are steroid-induced water and salt retention, further aggravated by increased extracellular volume and renin production caused by impaired graft function." (PMID 36013220, 2022). "It is noteworthy that hypertension is the most important independent risk factor for stroke, so the renin-angiotensin system in patients with post-stroke fatigue presents a pathological state." (PMID 35101070, 2022). "In people affected by MetS, hypertension (HTN) is probably related to renin‐angiotensin system activation and to the loss of insulin vasodilator effect on vessels." (PMID 34714544, 2022). "Risk factors for DN are chronic hyperglycemia and high blood pressure; the renin-angiotensin-aldosterone system blockade improves glomerular function and CV risk in these patients." (PMID 36013381, 2022). "Primary aldosteronism (PA) is the first and most common cause of secondary hypertension characterized by high blood pressure, adrenal hyperplasia, hyperaldosteronism, low renin concentration and often hypokalaemia." (PMID 35732960, 2022). "The third possible explanation for the association between excess alcohol consumption and high blood pressure is renin-angiotensin-aldosterone system stimulation, increased sympathetic activity, vasoconstriction, and elevated oxidative stress." (PMID 36227880, 2022).
Hypertension (continued). "Preliminary evidence suggests that activation of an adipose renin–angiotensin system is associated with high blood pressure in a visceral fat model." (PMID 35846316, 2022). "The present study aims to investigate the relationship between vitamin D deficiency and renin-angiotensin-aldosterone levels in patients with essential hypertension." (PMID 35814306, 2022). "It has been shown that up-regulation of the renin-angiotensin-aldosterone system (RAAS) is an important risk factor for the development of hypertension." (PMID 34946242, 2021). "Several pathogenic mechanisms have been proposed to explain the association between diabetes and hypertension, including the incretin‐mediated control of the renin–angiotensin–aldosterone system and alterations in calcium–calmodulin system." (PMID 34277988, 2021). "Nebivolol releases NO, thereby preventing the development of hypertension associated with chronic NO deficiency, and this effect appears to be dependent on inhibition of the renin-angiotensin system." (PMID 33809023, 2021). "Li J, Wang X, Chen J, Zhang H, Deng A. Association of renin-angiotensin system inhibitors with severity or risk of death in patients with hypertension hospitalized for coronavirus disease 2019 (COVID-19) Infection in Wuhan, China." (PMID 34287571, 2021). "Disorders involving the renin–angiotensin system (RAS) are also causative factors in the development of hypertension." (PMID 34828976, 2021). "The human ortholog of CG8773/CG8774 is predicted to be ENPEP, a member of the renin-angiotensin system that controls blood pressure and hypertension; known risk factors for atrial fibrillation (AF)." (PMID 33561224, 2021). "Specifically, miRNAs implicated in hypertension include endothelial miRNAs, renal miRNAs, miRNAs targeting vascular smooth muscle cells, and miRNAs targeting the renin–angiotensin–aldosterone system (RAAS)." (PMID 34769116, 2021). "Renal vein renin sampling can lateralize and even localize an ischemic focus which is causing hypertension and help direct selective treatment." (PMID 33411105, 2021). "Aliskiren and triamterene are renin inhibitors used to treat hypertension; and torasemide is used to treat edema associated with heart, renal, and hepatic failures." (PMID 33716737, 2021). "Renin-angiotensin system blockade and metformin represent low cost and effective drugs for hypertension, kidney protection, diabetes treatment and weight loss." (PMID 33604197, 2021). "Conclusion and relevance: SNVs in the renin and angiotensin pathway are associated with lisinopril effectiveness in a pilot cohort of patients with uncontrolled hypertension." (PMID 33769277, 2021). "We encourage considering this unusual but important complication when packing of the abdomen has been carried out, and strongly recommend ruling out renin-mediated hypertension as a cause of post-operative hypertension in such cases." (PMID 33857767, 2021). "The renin-angiotensin system has been implicated in the pathogenesis of hypertension, diabetes, and CVD." (PMID 33498183, 2021). "Patients present more frequently with hypertension, most likely because of the more severe hypercortisolism, but ARMC5 variants have also been associated in African Americans with low renin hypertension, higher fasting glucose, and HbA1c." (PMID 34680514, 2021). "Vitamin D deficiency is also associated with hypertension because of the renin-angiotensin-aldosterone system activation and endothelial system dysfunction." (PMID 34653200, 2021). "Briefly, hypertension results from the action of UA, which causes vasoconstriction in the kidney due to decreased NO synthesis in the endothelium, with activation of the renin-angiotensin system." (PMID 34177370, 2021). "Li et al32 studied 362 patients with hypertension of case series of 1178 hospitalised patients with COVID in regard to the association of renin–angiotensin system inhibitors with severity or risk of death." (PMID 32943474, 2021).
Hypertension (continued). "REN rs2368564 polymorphism situated in the ninth intron of the renin gene has been actively studied for more than 20 years, and its association with arterial hypertension has been established." (PMID 34065198, 2021). "Persons with hypertension have an increased activity of the renin–angiotensin system, which causes systemic inflammatory processes leading to T2DM." (PMID 33670226, 2021). "The renin–angiotensin–aldosterone system is involved in the development of severe hypertension, and some polymorphisms of the angiotensin-converting enzymes (ACE) or angiotensinogen encoding genes are associated with early onset hypertension." (PMID 33430236, 2021). "Angiotensin II (AngII), a predominate metabolite of the renin-angiotensin system, is a potent vasoconstrictor mediating hypertension and is associated with vascular complications in patients with diabetes and CVD." (PMID 33498183, 2021). "As a common byproduct of the renin–angiotensin mechanism, Ang II is a powerful vasoconstrictor that induces hypertension and is linked to complications in cardiovascular diseases and diabetic patients." (PMID 34770863, 2021). "A link has also been detected between hyperuricaemia and hypertension in animal models, noting elevated renin expression suggesting the underlying mechanism involves the renin-angiotensin system." (PMID 33987709, 2021). "On the one hand, OSAHS can directly lead to hypoxia and indirectly cause hypertension, inflammation, oxidative stress, sympathetic nervous system activation, and activation of the renin–angiotensin–aldosterone system." (PMID 33896382, 2021). "Hypertension is associated with the activation of the renin-angiotensin system, and elevated angiotensin II has been linked to AF." (PMID 34384364, 2021). "Increased circulating levels of leptin, sympathetic overactivity, activation of the renin-angiotensin-aldosterone system, and renal compression participate in obesity caused hypertension." (PMID 33394136, 2021). "In the vasculature, hypertension-induced macrophage infiltration drives nitric oxide scavenging causing reductions in renal blood flow, which in turn induce renin secretion by juxtaglomerular cells." (PMID 34950686, 2021). "Previous studies on hypertension in ARA has shown that ARA causes hypertension through the renin-angiotensin system." (PMID 35003315, 2021). "The activation of the renin-angiotensin system (RAS) has been implicated in hypertension and hypertension-associated vascular complication." (PMID 34650444, 2021). "Calcitriol/VDR suppression of renin gene expression explains in part the causal association between increases in circulating 25(OH)D levels and reductions in blood pressure and hypertension demonstrated by Mendelian randomization analysis." (PMID 34950686, 2021). "The vasoconstriction, renin-angiotensin-system activation, and sodium and water absorption promoted by elevated sympathetic activity and cytokines would ultimately cause severe hypertension." (PMID 33446177, 2021). "R2 levels in those with a stenotic lesion sufficient to cause an elevated level of renin were similar to those with essential hypertension, indicating a protective effect of RAAS inhibition in maintaining oxygenation." (PMID 34070611, 2021). "The underlying mechanism of essential hypertension is complex, which associated with the complex molecular network of vascular metabolism, endothelial dysfunction, inflammation, and the renin–angiotensin-aldosterone system (RAAS), etc.28–30." (PMID 33568719, 2021). "There is evidence showing that visceral fat can cause high blood pressure through inducing sodium retention, insulin resistance, renin-angiotensin-aldosterone activation, alteration of vascular function, and secretion of related adipokines." (PMID 34594579, 2021). "Disruption of this communication pathway is associated with reduced TGF, dysregulation of renin secretion, and hypertension." (PMID 32848881, 2020).
Hypertension (continued). "Since the tumor cells secret excessive renin, clinically this tumor can often cause severe hypertension and sometimes hypokalemia, in which case it would be easy to distinguish from other renal tumors (e.g., renal cell carcinoma)." (PMID 32899070, 2020). "Nitric oxide (NO) deficiency, gut microbiota dysbiosis, and dysregulated renin-angiotensin system (RAS) during pregnancy are linked to the development of hypertension in adult offspring." (PMID 33008046, 2020). "In animal experiments, vitamin D was found to be a potent endocrine suppressor of renin biosynthesis: VDR -/- mice had elevated production of renin and angiotensin II, causing hypertension, cardiac hypertrophy, and increased water intake." (PMID 32429489, 2020). "Accumulating evidence shows that the hyper-activation of the tissue renin–angiotensin system (RAS) through angiotensin II type 1 receptor (AT1R) plays a pivotal role in the pathogenesis of hypertension and associated end-organ injury." (PMID 32112267, 2020). "NO inhibition by L-NG-Nitroarginine Methyl Ester (L-NAME) in pregnancy caused programmed hypertension in adult offspring, which was associated with increased messenger RNA (mRNA) of renin and ACE in offspring kidney." (PMID 32054074, 2020). "The link between adipose tissue renin-angiotensin-aldosterone system signaling and obesity-associated hypertension." (PMID 32401842, 2020). "Renal hypoperfusion from renal artery stenosis (RAS) activates the renin-angiotensin system, which in turn causes volume overload and hypertension." (PMID 32399343, 2020). "Various mechanisms such as the association of sleep duration and hypothalamic–pituitary– adrenal axis and also renin–angiotensin system have been suggested as the causal link between sleep duration and hypertension." (PMID 33262801, 2020). "A deficiency in 11-beta hydroxylase deficiency presents with hypertension and low renin and aldosterone levels; however, the patient was suspected of having 21-OH deficiency due to the normal blood pressure, and normal levels of renin and aldosterone." (PMID 31914016, 2020). "Expression of the ren gene (encoding renin in zebrafish), along with the inflammation and hypertension markers (ace and crp), was found significantly higher than that in AB wild-type controls." (PMID 32984406, 2020). "The renin-angiotensin-aldosterone system is widely implicated in diabetes, hypertension, and heart failure." (PMID 32624690, 2020). "In conclusion, JGCT is a rare benign tumor which typically causes hypertension, hyperaldosteronism, hyper-angiotensin, high serum renin, and hypokalemia in young adults of 20-30,s." (PMID 32441904, 2020). "Several mechanisms are considered involved in programmed hypertension, including NO deficiency, oxidative stress, epigenetic regulation, altered renin–angiotensin system and sodium transporters." (PMID 33041805, 2020). "Vitamin D deficiency causes pro-inflammatory macrophage infiltration in metabolic tissues and is linked to renin-mediated hypertension." (PMID 32968066, 2020). "It is possible that acute changes in NO modulate physiologic changes in CD-renin, while states of chronically suppressed or deficient NO contribute to sustained hypertension, although this requires further investigation." (PMID 33281610, 2020). "The Japanese population has been reported to have a lesser occurrence of C allele in low renin hypertension when compared to patients with normal or high renin concentrations." (PMID 32443509, 2020). "Among these, the accumulation of perirenal fat increases sodium reabsorption due to kidney compression and activates the renin–angiotensin–aldosterone system, causing the development of hypertension, insulin resistance, and atherosclerosis." (PMID 33158191, 2020). "Disruption of Cx40-mediated intercellular signaling leads to loss of pressure control of renin secretion and development of hypertension." (PMID 32585970, 2020).
Hypertension (continued). "In diet-induced vitamin D deficiency, miR-106b deletion prevents vitamin D-deficiency-induced, renin-dependent hypertension in mice, and macrophages from such mice are unable to activate JG cell renin production or release." (PMID 32968066, 2020). "Renal artery stenosis is a leading factor of secondary hypertension, and its progress is associated with overactivation of the renin-angiotensin-aldosterone system (RAAS)." (PMID 33145109, 2020). "Here the authors show that impaired vitamin D signaling in myeloid cells causes hypertension via macrophage-specific miR-106b-5p secretion, which activates renin production in the kidney." (PMID 32968066, 2020). "Brown and colleagues reported that populations with suppressed plasma renin activity (≤0.5 ng/mL/h) and high aldosterone levels were at increased risk of hypertension (HR 1.18; 95% CI 1.03-1.36)." (PMID 32266384, 2020). "Renal dysfunction, such as an increase in sodium and water retention, renin release, or renal vascular resistance, causes hypertension and, subsequently in the long-term run chronic kidney damage." (PMID 33240096, 2020). "Overactivation of renin-aldosterone-angiotensin system (RAS) is part of the pathogenesis of obesity-associated hypertension." (PMID 32252748, 2020). "This pathway is stimulated by the secreted factor endothelin 1 (EDN1) and the renin-angiotensin pathway ligand angiotensin II (causing cardiac hypertrophy in response to high blood pressure)." (PMID 32946788, 2020). "By contrast, for low-renin hypertension, a two-locus model that includes the GRK4 A142V variant and cytochrome P450 11B2 (CYP11B2) C-344 T was 77.8% predictive." (PMID 30621627, 2019). "Apparent mineralocorticoid excess (AME) refers to a rare autosomal recessive disorder leading to low renin hypertension due to alterations in HSD11B2 (16q22.1), which encodes for the corticosteroid 11-beta-dehydrogenase." (PMID 30832344, 2019). "Evidence for a causal role of renin in hypertension comes from clinical trials of aliskiren, a direct renin inhibitor." (PMID 31581667, 2019). "Renin is an enzyme secreted by the kidney and plays a key role in the pathogenesis of arterial hypertension and its consequent complication associated with cardiovascular and renal diseases." (PMID 31374890, 2019). "The link between vitamin D deficiency and hypertension can be explained by the activation of the renin-angiotensin-aldosterone system, increasing the vascular tone due to the release of angiotensin II." (PMID 31396293, 2019). "Low-renin hypertension is a frequent cause of hypertension, with a prevalence of 20%–30%, and higher in African Americans." (PMID 30832344, 2019). "Mice with deficiency of VDR (Vdr-/-) have increased levels of renin and consequently of AngII, resulting in hypertension and cardiac hypertrophy, lipid metabolism, cellular stress response, and changes in the vascular function." (PMID 31623356, 2019). "The main cause of hypertension is the inappropriate activation of the renin-angiotensin system (RAS), once angiotensin II and associated RAS are involved in the regulation of blood pressure, vasoconstriction, sodium intake, and potassium excretion." (PMID 31261912, 2019). "Experimental studies in animals have shown that placental renin, when released into the maternal circulation, can cause hypertension." (PMID 31551925, 2019). "Given these intricate cross talks and overlaps between the calcineurin pathways, hypertension signaling and the association of calcineurin, renin and antihypertensive medications, the elucidation of the exact mechanisms of WDR92/PPP3R1 region is warranted." (PMID 31754133, 2019). "Concurrent hyponatremia in hypertension is most commonly caused by renin-secreting tumors, renal ischemia, and renal artery stenosis after exclusion of medication-induced hypertension." (PMID 30791890, 2019).